DDX11 (DEAD/H-box helicase 11)
Diseases named in the same sentence as DDX11 in open-access papers (continued):
Sharing a sentence is not in itself a finding about the gene and the disease.
melanoma (continued). "Panel b, imaging analysis, performed 24 hr after transfection, did reveal the presence of the DDX11 siRNA in these melanoma cells." (PMID 23116066, 2012). "Similar to the strong expression of DDX11 detected in tissues representing advanced melanoma, subsequent immunoblot analysis revealed that DDX11 is also strongly expressed in cell lines representing VGP (lane a) and MGP melanoma (lanes b-d)." (PMID 23116066, 2012). "DDX11 has been shown to be associated with melanomas and lung cancer; however, no studies have been performed regarding its association with ccRCC." (PMID 34073906, 2021). "Moreover, immunohistochemistry studies confirmed that the DDX11 expression level is much higher in late-stage melanoma and melanoma-infiltrated lymph nodes compared to normal melanocytes, atypical nevocytes and MIS-derived tissues." (PMID 33802088, 2021). "Additionally, the inhibition of DDX11 expression decreases the proliferation rate of melanoma cells and induces apoptosis." (PMID 33823929, 2021). "Based on these results, Becker and colleagues proposed that DDX11 could be considered as a novel target in alternative strategies to cure advanced melanoma that are resistant to other pharmacological treatment or refractory to radiation therapy." (PMID 33802088, 2021). "Additionally, a previous study suggested that the DDX11 expression level is high in melanomas and plays a key role in cancer progression." (PMID 31413739, 2019). "DDX11 downregulation by siRNAs in cells derived from metastatic growth phase (MPG) melanoma had the following consequences: rapid and dramatic morphology alteration, sister chromatid cohesion defects, chromosome fragmentation, inhibition of cell proliferation, and massive apoptosis." (PMID 30469382, 2018). "Moreover, immunohistochemistry studies revealed higher expression of DDX11 in advanced melanoma and melanoma-infiltrated lymph nodes compared to epidermal melanocytes of normal skin, atypical nevocytes and MIS cells." (PMID 30469382, 2018). "In subsequent studies, which focused upon an analysis of fluorescently labeled as well as Giesma-stained chromosome spreads, a proliferation analysis and apoptosis assays, we determined the impact of suppressing DDX11 expression on melanoma cells representing advanced melanoma." (PMID 23116066, 2012). "Alternative splicing of the evolutionary highly conserved human DDX11 gene, located on chromosome 12p11, which is not a chromosomal locus that is altered in advanced melanomas, yields several transcript variants of slightly different length." (PMID 23116066, 2012). "Compared with the DAPI-stained chromosome spreads of melanoma cells that had been transfected for 24 hr with the control siRNA pool, the DAPI-stained chromosome spreads of DDX11 siRNA-transfected melanoma cells revealed a pattern of tightly condensed chromosomes." (PMID 23116066, 2012). "Furthermore, and even more apparent was that the average length of the chromosomes of the DDX11 siRNA-transfected melanoma cells was significantly shorter than the length of the chromosomes of the control siRNA-transfected melanoma cells." (PMID 23116066, 2012). "The most prominent phenotypic change we observed during this series of experiments was that compared with control siRNA transfected cells, melanoma cells that had been transfected with the DDX11 siRNA, exhibited a rapid and dramatic alteration in their morphology." (PMID 23116066, 2012). "In this report, we show that the helicase DDX11 is expressed at high levels in primary and metastatic melanoma, and that interfering with its expression leads to severe chromosome segregation defects, telomere shortening, and massive melanoma cell apoptosis." (PMID 23116066, 2012). "Furthermore, our data demonstrate that interfering with the expression of DDX11 has severe consequences for melanoma cells." (PMID 23116066, 2012).
melanoma (continued). "Furthermore, and equally important, we demonstrate that blocking the expression of DDX11 leads not only to inhibition of melanoma cell proliferation and severe defects in chromosome segregation, but also drives melanoma cells rapidly into massive apoptosis." (PMID 23116066, 2012). "The data, summarized herein, provide not only further and strong support for this observation, but also demonstrate that inhibiting expression of a helicase such as DDX11, which has a vital function in sister chromatid cohesion, is deleterious for melanoma cells." (PMID 23116066, 2012). "Taken together, these data suggest that molecular targeting of DDX11 could be a new avenue and powerful approach to treat advanced melanoma, which is refractory to chemotherapy and radiation therapy." (PMID 23116066, 2012). "Besides, immuno-histochemistry analyses have shown that the DDX11 protein is over-expressed in many cancerous tissues compared to neighboring healthy counterparts, such as in hepatocellular carcinomas, osteosarcoma, melanoma and lung adenocarcinoma." (PMID 33802088, 2021). "The biochemical functions of DDX11 have been established, but hitherto, a DDX11-specific small-molecule inhibitor is not available that would make it possible to systemically treat human melanoma xenografts and establish in vivo, therapeutic efficacy of blocking the function of DDX11." (PMID 23116066, 2012). "Thus, it is possible that like DDX39, which when overexpressed leads to progressive telomere elongation and to telomere shortening when depleted, DDX11 has an important function in maintaining telomere length and stability in a malignancy such as advanced melanoma." (PMID 23116066, 2012). "Some of these include Dead H box helicase 11 (DDX11), Claudin 5 (CLDN5), chemokine CXC motif (CXCL1 ligand 1, melanoma growth), glutathione S-transferase mu 1 (GSTM1), major histocompatibility complex class I K (HLA-K), and thrombospondin 1 (THBS1)." (PMID 36769056, 2023). "The most significant differences in melanoma are NOMO1, PIGT, VKORC1, PDIA5 and DDX11, and the most significant differences in uterine cancer are CTU2, EMC8, TUBG1, CLPP and LONP1." (PMID 34951103, 2022). "Research published by the Becker group reported the identification of DDX11 as a gene that is upregulated eight-fold in radial growth phase (RGP) melanoma, the first stage of invasive melanoma, compared to non-invasive melanoma in situ (MIS)." (PMID 33802088, 2021). "For example, DDX39 is overexpressed in MM tissues, and its downregulation inhibits the proliferation and invasion of melanoma cells; In WM1158 melanoma cells, disruption of DDX11 expression induces apoptosis." (PMID 34233596, 2021). "Although this finding has been reported in studies on DDX11-/- mice, which show that DDX11 depletion induces apoptosis, no other studies—except those on melanoma —have shown that rapid programmed cell death is induced in response to DDX11 downregulation." (PMID 34073906, 2021). "Upregulation of DDX11 was documented in lung adenocarcinoma, osteosarcoma, advanced melanoma, and HCC, which indicate that DDX11 may exert pro-tumor activity." (PMID 33614480, 2020).
lung adenocarcinoma (9 papers, 2019 to 2024). A carcinoma that arises from the lung and is characterized by the presence of malignant glandular epithelial cells. "In patients with lung adenocarcinoma, upregulated DDX11 expression is associated with poor prognosis." (PMID 33823929, 2021). "Moreover, DDX11 was significantly upregulated and associated with a poor prognosis in patients with lung adenocarcinoma." (PMID 32392781, 2020).
Fanconi anemia (7 papers, 2013 to 2021). Fanconi anemia (FA) is a hereditary DNA repair disorder characterized by progressive pancytopenia with bone marrow failure, variable congenital malformations and predisposition to develop hematological or solid tumors. "The XPD helicase family comprises XPD and several related super-family 2 DNA helicases including DDX11/ChlR1 (DEAD/DEAH box helicase 11), RTEL1 (regulator of telomere elongation 1), and FANCJ (Fanconi anemia complementation group J)." (PMID 34660592, 2021).
microcephaly (6 papers, 2012 to 2024). A congenital or acquired developmental disorder in which the circumference of the head is smaller than normal for the person's age and sex. "In support of this, a patient with a mutation in a gene encoding the DNA helicase DDX11/ChlR1 had microcephaly, premature sister chromatid separation, and genome instability." (PMID 22988450, 2012). "For example, DDX11 is critical in pathology of microcephaly." (PMID 38045239, 2024). "We observed one single m6A site near the stop codon in 7 microcephaly-related E-SMRs, including Brca2, Cep152, Ddx11, Nde1, Kif14, Stil and Cdk5rap2, 3 polymicrogyria-related E-SMRs (Eomes/Tbr2, Pax6 and Foxp2), and 3 megalencephaly-related E-SMRs (Gli3, Ccnd2 and Kif7)." (PMID 32992647, 2020).
hepatocellular carcinoma (5 papers, 2020 to 2024). A malignant tumor that arises from hepatocytes. "DDX11-AS1—DEAD box 11 antisense RNA1 (also known as ATP-dependent DNA helicase DDX11) is transcribed from a gene located on chromosome 12p11.21 which has been evidenced in a study on hepatocellular carcinoma in 2017." (PMID 35004666, 2021). "Additionally, the E2F1/DDX11 axis is capable of promoting malignant behaviors of hepatocellular carcinoma cells via activation of the PI3K/AKT/mTOR signaling pathway." (PMID 36777627, 2023).
lung carcinoma (5 papers, 2018 to 2022). "Second, we knocked down DDX11’s expression in lung cancer (A549) and colon cancer (HCT116) cell lines, respectively." (PMID 36474250, 2022). "Moreover, Kaplan–Meier analysis of the probability of survival of cancer patients divided in two groups by DDX11 median expression shows that high levels of DDX11 expression significantly correlate with decreased overall survival of patients with ovarian and lung cancers." (PMID 33879618, 2021).
ovarian carcinoma (4 papers, 2013 to 2021). A malignant neoplasm originating from the surface ovarian epithelium. "Specifically, DDX11 is highly up-regulated or amplified in diverse cancers, such as breast and ovarian cancers, including one-fifth of high-grade serous ovarian cancers (cBioPortal and The Cancer Genome Atlas [TCGA])." (PMID 33879618, 2021). "Silencing of DDX11 using siRNA reduced cell viability in a series of ovarian cancer cell lines, namely UWB1.289 + BRCA1, OVCAR8, IGROV1, and COV362 as assessed by crystal violet staining of viable cells upon chronic cisplatin and olaparib drug treatment for 5 to 6 d." (PMID 33879618, 2021). "Thus, DDX11 targeting sensitizes ovarian cancer cell lines to chemotherapy." (PMID 33879618, 2021). "We aimed to examine whether targeting DDX11 by small interfering RNA (siRNA) affects cell viability in ovarian cancer cell lines exposed to baseline therapy constituted by cisplatin and olaparib, as previous results suggested a role for vertebrate DDX11 in the tolerance of such lesions." (PMID 33879618, 2021).
clear cell renal cell carcinoma (3 papers, 2020 to 2021). "In clear cell renal cell carcinoma (ccRCC), CLIP4 mutations are three-fold higher in patients with aggressive tumors than in those without aggressive ccRCC, and high expression levels of MOCOS, BAIAP2L1, DDX11, and CLIP4 are markedly associated with poor OS." (PMID 33575272, 2020).
renal cell carcinoma (2 papers, 2021 to 2023). "Genes associated with the DEAD-box helicase DDX11 are significant biomarkers of aggressive renal cell carcinoma (RCC), but their molecular function is poorly understood." (PMID 34073906, 2021). "DDX11, a helicase involved in sister chromatid cohesion, was identified as a significant biomarker of aggressive renal cell carcinoma (RCC) in our previous studies." (PMID 34073906, 2021). "Deadbox helicase 11 (DDX11) is a biomarker of aggressive renal cell carcinoma, with no expression in healthy kidneys and increasing expression as the stage of renal cell carcinoma increases." (PMID 37508568, 2023). "Importantly, DDX11 knockdown also significantly induced sensitivity to PARPi by Olaparib compared to Olaparib alone, pointing towards DDX11 as a biomarker for PARP therapy in renal cell carcinoma." (PMID 37508568, 2023).
acute myeloid leukemia (1 paper, 2020). Acute myeloid leukemia (AML) is a group of neoplasms arising from precursor cells committed to the myeloid cell-line differentiation. "In addition, our data further showed that DDX11 mRNA expression was able to distinguish the clinical outcomes in several TCGA cancers, such as adrenocortical carcinoma (ACC) and acute myeloid leukemia (LAML)." (PMID 33614480, 2020).
anaplastic large cell lymphoma (1 paper, 2018). Anaplastic large cell lymphoma (ALCL) is a rare and aggressive peripheral T-cell non-Hodgkin lymphoma, belonging to the group of CD30-positive lymphoproliferative disorders, which affects lymph nodes and extranodal sites. "Moreover, it was reported that in the colorectal cancer cell lines HCT116 and DLD1 and in ALK-positive anaplastic large cell lymphoma (ALCL), an aggressive form of non-Hodgkin lymphoma, DDX11 protein expression level is reduced, leading to genomic instability and chromatid cohesion defects." (PMID 30469382, 2018).
benign renal tumors (1 paper, 2021). "Immunohistochemistry and immunoblotting determined DDX11 expression in normal kidney tissues, benign renal tumors, and RCC tissues and cell lines." (PMID 34073906, 2021). "Subsequent immunoblot analysis revealed strong DDX11 expression in advanced and high-grade ccRCC, but no DDX11 expression was observed in normal kidney tissues or benign renal tumors." (PMID 34073906, 2021). "DDX11 was upregulated in high-grade, advanced RCC compared to low-grade, localized RCC, and DDX11 was not expressed in normal kidney tissues or benign renal tumors." (PMID 34073906, 2021).
colon adenocarcinoma (1 paper, 2020). "Using TCGA data, we firstly assessed the expression of DDX11 in TCGA gastrointestinal cancers, including liver hepatocellular carcinoma (LIHC), colon adenocarcinoma (COAD), esophageal carcinoma (ESCA), pancreatic adenocarcinoma (PAAD), rectum adenocarcinoma (READ), and stomach adenocarcinoma (STAD)." (PMID 33614480, 2020).
dyskeratosis congenita (1 paper, 2020). Dyskeratosis congenita (DC) is a rare ectodermal dysplasia that often presents with the classic triad of nail dysplasia, skin pigmentary changes, and oral leukoplakia associated with a high risk of bone marrow failure (BMF) and cancer. "The RTEL1 helicase, mutated in Dyskeratosis congenita (DC) or its more severe form Hoyeraal-Hreidarsson syndrome (HHS), and the DDX11 helicase mutated in Warsaw Breakage syndrome (WBS) have most recently joined the group of clinically relevant Fe-S DNA helicases." (PMID 32120966, 2020).
glioma (1 paper, 2019). A benign or malignant brain and spinal cord tumor that arises from glial cells (astrocytes, oligodendrocytes, ependymal cells). "DDX11, also known as CHL-1, is able to promote cell proliferation, metastasis, and migration in human glioma cells." (PMID 30841487, 2019).
liver cancer (1 paper, 2021). An epithelial or non-epithelial malignant neoplasm that arises from the liver. "The gene DDX11 has mutations in 5 liver cancer samples, while PPP2R5B has mutations in 3 samples." (PMID 34094926, 2021).
lymphoid cancer (1 paper, 2023). "Mutations in two novel genes, CHD1 and DDX11, demonstrated a negative impact on survival in AML/MDS and lymphoid cancer data from the Cancer Genome Atlas (TCGA)." (PMID 37041565, 2023).
metastatic melanoma (1 paper, 2012). A melanoma that has spread from its primary site to another anatomic site. "The novel finding presented herein documents that DDX11, a member of the DEAD-box family of helicases, is expressed at high levels in primary and metastatic melanoma, but not in melanocytes of normal skin." (PMID 23116066, 2012).
myelodysplastic syndrome (1 paper, 2024). A clonal hematopoietic disorder characterized by dysplasia and ineffective hematopoiesis in one or more of the hematopoietic cell lines. "In multivariate analyses conducted in a CIBMTR study, it was revealed that DDX11 mutations affect survival by increasing the risk of both relapse and transplant-related mortality in patients with myelodysplastic syndrome." (PMID 39767827, 2024).
ovarian serous cystadenocarcinoma (1 paper, 2021). A malignant serous cystic epithelial neoplasm arising from the ovary. "DDX11 is overexpressed in various cancers and amplified in 21% of ovarian serous cystadenocarcinoma (TCGA Pan-Cancer Atlas and CBioPortal)." (PMID 33879618, 2021).
viral infection (1 paper, 2024). "The collective findings revealed that DDX11 was dependent on MAVS to accumulate in mitochondria after viral infection, which enhanced the formation of the RIG-I-MAVS complex." (PMID 39470258, 2024). "To assess the biological relevance of DDX11 in viral infection, we analyzed the effects of its overexpression on the replication of SADS-CoV." (PMID 39470258, 2024). "Consequently, upon viral infection of host cells, viral RNA may first encounter DDX11 before being recognized by RIG-I." (PMID 39470258, 2024). "Here, we provided several lines of evidence to demonstrate that DDX11 acted as a co-receptor to promote viral RNA binding to RIG-Ι, and the interaction of RIG-Ι and MAVS upon viral infection." (PMID 39470258, 2024). "Because knockdown or knockout of DDX11 suppressed the production of IFN-β induced by SeV and poly(I:C), the potential regulatory role of DDX11−/− HEK293T cells on viral infection and proliferation was investigated." (PMID 39470258, 2024). "Finally, DDX11 interacted with MAVS, and this interaction was increased after viral infection." (PMID 39470258, 2024).
Xeroderma pigmentosum complementation group D (1 paper, 2021). Xeroderma pigmentosum complementation group D (XPD) is a subtype of xeroderma pigmentosum (XP; see this term), a rare photodermatosis predisposing to skin cancers. "Fe-S family helicases, including FANCJ, DDX11/ChlR1, xeroderma pigmentosum complementation group D (XPD), and regulator of telomere elongation helicase 1 (RTEL1), are closely related to G4 function modulation." (PMID 34912850, 2021).